LGALS3 (galectin 3)
Diseases named in the same sentence as LGALS3 in open-access papers (continued):
Sharing a sentence is not in itself a finding about the gene and the disease.
cancer (continued). "In contrast to the galectin-3 findings, Beclin1 was generally down regulated in all tissue types and in many cancer subtypes." (PMID 22039439, 2011). "High expressions of galectin-3 in some human cancers indicate progression and metastatic activity of cancer, i.e breast, kidney, and thyroid." (PMID 22039439, 2011). "High levels of circulating galectin-3 are correlated with an increased potential for malignancy in several types of cancer." (PMID 21686160, 2011). "It has been reported that human galectin-1 (Gal-1) and galectin-3 (Gal-3) can perform their cancer-related functions via specifically recognizing TF antigen." (PMID 21949831, 2011). "The biofunctionally conjugated SWCNT showed electrochemical sensing levels in the nanoscale range for detecting the cancer marker galectin-3." (PMID 21686160, 2011). "The ratios of cancer to normal tissue levels of galectin-3 and Beclin1 were calculated (using the mean for each tissue type)." (PMID 22039439, 2011). "Galectin-3 and Beclin1 roles in cancer progression and treatment response are supported by the expression patterns in this study." (PMID 22039439, 2011). "In the ovaries, both galectin-3 and Beclin1 levels were lower in cancers compared to normal ovarian tissues." (PMID 22039439, 2011). "The findings support the known effects of galectin-3 on the behavior and progression of certain human cancer types." (PMID 22039439, 2011). "Further studies are clearly needed to establish the role of galectin-3 in cancer metastasis and its suitability as a therapeutic target for selected cancers." (PMID 21966428, 2011). "d-(+)-Galactose-conjugated single-walled carbon nanotubes (SWCNTs) were synthesized for use as biosensors to detect the cancer marker galectin-3." (PMID 21686160, 2011). "Relative mRNA expressions for galectin-3 were higher than for Beclin1 in all tissue (normal and cancer) types." (PMID 22039439, 2011). "Galectin-3 expression patterns in normal and cancer tissues support its reported roles in human cancer." (PMID 22039439, 2011). "Here, we determined the binding affinity of d-(+)-galactose-conjugated CNTs for the detection of the cancer marker galectin-3." (PMID 21686160, 2011). "In cancer tissues, breast, kidney, thyroid and prostate had the highest galectin-3 mRNA levels compared to normal tissues." (PMID 22039439, 2011). "Other earlier studies have found variable correlation between cancer and serum levels (low μg/ml) of the Mac-2-binding protein, named based on its affinity for galectin-3." (PMID 22028908, 2011). "This indicates that d-(+)-galactose-conjugated SWCNTs are potentially useful electrochemical biosensors for the detection of cancer marker galectin-3." (PMID 21686160, 2011). "Beclin1 level was higher in cancer than normal liver tissues while galectin-3 was low though higher in cancer than normal tissues." (PMID 22039439, 2011). "High galectin-3 expressing cancer tissues were breast, prostate, kidney and thyroid when compared to normal tissues." (PMID 22039439, 2011). "The aim of the study was to determine expression levels of galectin-3 and Beclin1 in both normal and cancer tissues and correlate expression patterns in cancer types." (PMID 22039439, 2011). "73.7% of the cancer patients showed higher expression levels of galectin-3 and 70% of them showed higher PAR-1 and MMP-1 levels in their malignant tissues than in their normal counterparts." (PMID 21966428, 2011). "This study is intended to provide preliminary information on the potential of d-(+)-galactose-conjugated CNTs as efficient nanobiosensors for the detection of the cancer marker galectin-3." (PMID 21686160, 2011). "Several other investigators showed that galectin-3 is very useful in distinguishing benign from malignant tumors, especially PTC, with high sensitivity and specificity." (PMID 20181018, 2010).
cancer (continued). "The sensitivity and specificity of galectin-3 immunodetection alone in discriminating benign from malignant thyroid lesions were more than 99% and 98% respectively, and the positive predictive value and diagnostic accuracy were 92% and 99%." (PMID 23658855, 2010). "of all 54 malignant tumors, 46 (85.1%) were positive for galectin-3 and CK19, 45 (83.3%) were positive for Ret and 47 (87%) positive for HBME-1." (PMID 20181018, 2010). "The staining results showed that malignant tumors express galectin-3, HBME-1, CK19 and Ret oncoprotein significantly more than benign nodules." (PMID 20181018, 2010). "Median value of serum galectin-3 concentration was 1068 pg/mL in the cancer group vs. 584 pg/mL in controls." (PMID 23658855, 2010). "The galectin-3-MUC-induced cell aggregation increases the survival of the cancer cells by preventing initiation cellular anoikis (suspension-induced apoptosis)." (PMID 20565834, 2010). "Silencing of galectin-3 resulted in altered cancer cell morphology, reduced fascin-1 expression, decreased cell motility, and reduced malignant cell invasion." (PMID 23658855, 2010). "This study shows that the presence of galectin-3 at pathologically-relevant circulating galectin-3 concentrations increases cancer cell homotypic aggregation by interaction with cancer-associated MUC1 that expresses the TF disaccharide." (PMID 20565834, 2010). "Determination of galectin-3 levels in urine of cancer patients and healthy controls established a strong correlation between the stages of the disease with galectin-3 concentration." (PMID 23658855, 2010). "In our study, galectin-3 showed 85.2% sensitivity for immunoexpression distinction between carcinomas and benign nodules (positive in 27.5% of benign vs. 85.1% of malignant nodules)." (PMID 20181018, 2010). "The markers were expressed in approximately half the cases of benign tumors compared to over 85% expression in the malignant tumors (92.6% for galectin-3)." (PMID 19826479, 2009). "The sensitivity and specificity of the markers for the diagnosis of benign and malignant tumors were again highest with galectin-3 at 92.6% and 71.4%, respectively." (PMID 19826479, 2009). "Galectin-3 showed the highest immunoexpression in malignant tumors (25/27, 92.6%) and lowest reaction in benign lesions (10/44, 22.7%)." (PMID 19826479, 2009). "A forced expression of galectin-3 via specific cDNA transfection generates a transformed phenotype, blocking the apoptotic program, a feature that favors the development of cancer." (PMID 19020658, 2008). "Decreased expression of p27, an inhibitor of cyclin-dependent kinase, and abnormal galectin-3 expression have been shown in carcinomas." (PMID 19016595, 2008). "In order to evaluate the binding specificity of a 99mTc-labeled mAb to galectin-3 in vivo, six animals bearing galectin-3 positive carcinoma xenografts (ARO-Gal-3+) were considered in a preliminary experiment." (PMID 19020658, 2008). "For example, CD44 and galectin 3, genes relevant for cancer metastasis, were up-regulated in peritoneal metastasis." (PMID 12402156, 2002). "Galectin-3 is involved in the growth, adhesion, and metastasis of cancer cells." (PMID 41249064, 2025). "In contrast to other galectins, such as Galectin-3, which have been studied in the context of various cancer subtypes, our findings underscore the unique importance of galectin-8 in regulating drug resistance mechanisms through its influence on cell survival pathways​ 27, 30-32." (PMID 39895791, 2025). "Thus, non-carbohydrate small molecule compounds K2 and L2 are potent galectin-3 inhibitors that can effectively inhibit galectin-3-mediated actions in cancer progression and metastasis both in vitro and in vivo." (PMID 41023585, 2025).
cancer (continued). "The discovery of these non-carbohydrate galectin-3 inhibitors offers significant promises to the development of galectin-3-targeted therapeutic drugs for the treatment of cancer and other galectin-3-mediated pathologies such as inflammation and fibrosis-associated diseases." (PMID 41023585, 2025). "Notably, levels of circulating galectin-3 are increased in cancer patients, promoting metastasis through its interaction with cancer-associated mucin 1; this causes mucin 1 polarization and exposure of smaller cell surface adhesion molecules." (PMID 40284554, 2025). "Furthermore, urine levels of galectin-3 have been recognized as a biomarker for heart failure and several types of cancer." (PMID 40649879, 2025). "Several pharmacological inhibitors of Galectin-3 that block its carbohydrate recognition domains exist, including TD-139, which is currently being investigated in clinical studies for its therapeutic potential in fibrotic, cancer and inflammatory disorders." (PMID 40161708, 2025). "Galectin-3 (Gal-3) plays an important role in adhesion and proliferation of cancer cells." (PMID 40481460, 2025). "We found that the secreted factor LGALS3 played a key role in establishing the positive feedback loop between cancer cells and MDMs, which may be an attractive therapeutic target." (PMID 39629136, 2024). "It is worth mentioning that no expression of PD-L1 could be observed, whereas three (HLA-DR, FGL-1, and galectin-3) of the multiple ligands for LAG-33 were highly expressed in both cancer and stromal cells." (PMID 38336861, 2024). "In addition to the 5FU selectivity, another major objective of this sugar modification is to establish the therapeutic benefit of MR on galectin-3 (Gal-3) expressing cancer cells as a prodrug of 5FU." (PMID 38790896, 2024). "Of notice, galectin-3 itself is posttranslationally modified in distinct cancer tissues." (PMID 38990375, 2024). "The high expression of LGALS3 might promote cancer invasion and impede the function of the immune system to make the cell apoptosis, leading to cancer recurrence." (PMID 38671151, 2024). "Moreover, we described 5 genes associated with hypoxia high status, of which the top 3 (LGALS3, CD276 and NT5E) have already been identified as targets of interest in cancer." (PMID 38510243, 2024). "LGALS3 plays a significant role in cancer progression by influencing immune responses." (PMID 39124881, 2024). "Furthermore, modified heparin derivatives demonstrate potential in blocking galectin 3-mediated cancer cell adhesion and angiogenesis, offering a new frontier in anti-metastasis and anti-cancer drug development." (PMID 39459002, 2024). "Furthermore, the loss of association between galectin-3 and β4-integrin via β1,6GlcNAc-branched N-glycans abolishes galectin-3–promoting cancer cell adhesion to the extracellular matrix proteins and migration." (PMID 38534381, 2024). "Similarly, galectin-3 (Gal-3) is involved in various aspects of cancer progression, including proliferation, angiogenesis, metastasis, and immune evasion." (PMID 39518152, 2024). "Cxcl16 and Lgals3 were related to Cancer-B1/2/3-TME, while Retnla was related to Cancer-B4-TME." (PMID 39695088, 2024). "The role of Galectin-3 in cancers was analyzed in the thyroid." (PMID 39685748, 2024). "This potential hypoxia/galectin-3/Rho/ROCK pathway may be used as a predictive biomarker for when ROCK inhibition may be effective in cancer treatment." (PMID 38921484, 2024). "Interestingly, phosphorylation also seems to determine the intracellular fate of galectin-3 in cancer cells." (PMID 38990375, 2024). "The different roles of LGALS3 may be attributed to different potential mechanisms that appear cancer-type dependent." (PMID 38643145, 2024). "Interestingly, most genes were up-regulated in multiple groups; genes for chemokines (Ccl2, Ccl5), cell adhesion (Icam1, Lgals3) and a growth factor (Ngf) were up-regulated in at least three non-cancer groups." (PMID 39254423, 2024).
cancer (continued). "Notably, Lgals3 which was up-regulated by TAA in non-cancer groups was also up-regulated in SB/AKT/c-Met + TAA (3.8-fold) and SB/AKT/NRas + TAA (4.1-fold)." (PMID 39254423, 2024). "Galectin 3 (Gal3) is involved in promoting proliferation and metastasis, stimulating angiogenesis, mediating immune suppression, and chemotherapeutic resistance in various carcinomas." (PMID 38438589, 2024). "Galectin-3 is commonly overexpressed in most types of cancer and promotes multiple steps in cancer progression and metastasis such as cancer cell adhesion, invasion and angiogenesis by interaction with galactose-terminated cell surface or extracellular matrix glycans." (PMID 37612278, 2023). "The studies show that cancer-associated MUC1 mucin is one of the most desirable, natural ligands for galectin-3, and that such interactions are mediated mostly via the binding of Gal-3 to the T carbohydrate, a prominent tumor-associated antigen on MUC1 mucin." (PMID 37345016, 2023). "In addition, activation of the β-catenin pathway by galectin-3 has been reported in multiple cancer types." (PMID 37762705, 2023). "However, studies investigating plasma galectin-3 levels in patients receiving systemic cancer therapies (e.g., anthracycline, doxorubicin, trastuzumab) show disappointing results." (PMID 37796395, 2023). "Next, we examined the binding of galectin-3 to Trop-2, because Trop-2 is a highly glycosylated membrane protein, and Trop-2 and galectin-3 exhibited similar distribution patterns in various human cancer tissues." (PMID 37380081, 2023). "GB1211 has high affinity for galectin-3 (0.025 ± 0.0017 μM) with good oral bioavailability in animals (68% in mice) and is currently in development for the treatment of cancer and fibrotic disorders including NSCLC (identifier: NCT05240131) and cirrhosis (identifier: NCT05009680), respectively." (PMID 36914828, 2023). "In addition to galectin-3 promoting pro-oncogenic roles in cancer cells, it also acts on other immune cells for immunosuppression." (PMID 37371482, 2023). "Galectin-3 is a multi-mode promoter in cancer development, progression and metastasis." (PMID 37612278, 2023). "Interestingly, previous studies have accumulated pieces of evidence that galectin-3 directly binds to integrins and growth factor receptors on cancer cells to activate cellular malignant processes, including cell proliferation, invasion, and chemoresistance." (PMID 38052804, 2023). "Multimerization of galectin-3 often points to its activity in cancer and inflammation processes." (PMID 37345016, 2023). "It is a competitive inhibitor of the galectin-3 protein, which is involved in cancer pathogenesis." (PMID 37630724, 2023). "Thus, the influence of MUC1/T antigen—galectin-3 interactions on cancer development raises promising therapeutic strategies involving the inhibition of such interactions." (PMID 37345016, 2023). "Furthermore, several genes whose expression predicts the poor prognosis of many cancer types and represents potential anticancer targets, i.e., Lgals3, Smox, Ndrg1, Neat1, and Rbm39, were significantly upregulated in most of the KO cell types." (PMID 37809094, 2023). "Cancer cells secrete galectin-3 within the TME to serve in a general immunosuppressive role." (PMID 37371482, 2023). "In addition, E-cadherins, the upregulation of N-cadherins by galectin-3, results in adhesion and invasion of cancer cells through the stroma." (PMID 37444377, 2023). "Galactose lectin-3 (LGALS3, also known as galectin-3), a member of the galectin protein family, is one of the most widely studied galactose lectins in cancer and is involved in a variety of cellular activities including apoptosis, cell migration, proliferation, and angiogenesis." (PMID 37415742, 2023). "Galectin-3 could inhibit the interaction of NK cells with cancer cells, thereby evading the ability of cytotoxic effects of NK cells to kill them." (PMID 36873388, 2023).
cancer (continued). "The discovery in this study that galectin-3 increases the secretion of Cathepsin-B, MMP-1, and MMP-13 by cancer cells suggests that increasing the secretion of proteases is probably one of the mechanisms behind galectin-3-mediated cancer promotion reported in many previous studies." (PMID 37055381, 2023). "Galectin-3, a product of the LGALS3 gene, is frequently associated with malignancy." (PMID 36555445, 2022). "Galectin-3, a pleiotropic protein, has a carbohydrate binding domain and exists in intra- and extra-cellular sites, and plays relevant biological roles in different diseases, among which fibrosis, cancer and heart diseases deserve a special mention." (PMID 36076865, 2022). "Therefore, additional multicenter studies with substantial sample sizes are required to corroborate the assessment of the predictive potential of galectin-3 in cancer-therapy-related cardiotoxicity." (PMID 36551214, 2022). "Targeting galectin-3 becomes a potential therapeutic to improve immune responses against cancer." (PMID 35927755, 2022). "In addition, pectic polysaccharides can selectively bind to galectin-3 (Gal-3), which is a potential target for cancer therapy and involved in cell proliferation, adhesion, and regulation of the cell cycle, to prevent and reduce cancer progression." (PMID 36615741, 2022). "Functions and expression of galectin-3 were repeatdly studied in several types of cancers." (PMID 37305017, 2022). "Secreted galectin 3 is known to support cancer cell migration in various ways." (PMID 36123693, 2022). "This analysis aimed to evaluate whether Galectin-3 levels are frequently elevated in response to cancer therapy." (PMID 36551214, 2022). "Galectin-3 is involved in many different diseases and conditions, including cancer and fibrosis." (PMID 36499368, 2022). "Moreover, T antigen overexpression was associated with increased invasive capacity and stem-like properties of cancer cells, as well as with cancer cells metastatic potential irrespectively of galectin-3 assessment." (PMID 35428302, 2022). "Galectin-1 and Galectin-3 overexpression has been widely associated with worse outcomes in many cancers, in which they can be expressed by both cancer cells as well as non-cancer stromal cells." (PMID 36430839, 2022). "In addition, interaction of circulating galectin-3 with cancer cell surface MUC1 was shown to prevent anoikis." (PMID 35410995, 2022). "As the PNA glycan binding profile overlaps considerably with that of galectin-3, we speculated that circulating PNA might mimic the actions of circulating galectin-3, thus promoting cancer cell metastasis." (PMID 34223877, 2021). "The counter receptor for GPVI is galectin-3, which is expressed on cancer cells." (PMID 34290095, 2021). "Nevertheless, galectin-3 has a regulatory role in cancer stemness related pathways beside other pathways the EGFR/FGFR pathway is also involved and it was published that OPN induced migration and invasion is strongly associated with activation of different EGF receptors." (PMID 34257527, 2021). "The biomarkers on the surface of the cancer cell membrane, such as T antigen-Galectin-3 and EpCAM, make cancer cells have homologous targeting and immunogenicity, which could overcome the environment of immune clearance and nonspecific attachment in vivo." (PMID 34596000, 2021). "We also hypothesized that GPVI–galectin-3 interaction eventually leads to the activation of the downstream nuclear factor κβ (NF-κβ) pathway in cancer cells." (PMID 34290095, 2021). "Galectin-3 is expected to become a new therapeutic target for cancer and CTRCD." (PMID 34859069, 2021). "Galectin-3 is upregulated in cancer cells, and promotes cancer progression and metastasis." (PMID 34859069, 2021). "Galectin-3 is highly expressed in different cancers, including melanoma and colorectal cancer." (PMID 34073528, 2021). "Galectin-3 has a good discriminative power to differentiate benign thyroid nodules from cancer." (PMID 34035807, 2021).